RN7SKP95 (RN7SK pseudogene 95)
Gene: Miscellaneous RNA gene on chromosome 15 (58,703,852 to 58,704,154, reverse strand). Ensembl gene ENSG00000199730.
Homologues: Orthologues: chimpanzee 7SK (99% identical), mouse Gm55999 (71% identical), mouse Gm54849 (59% identical). Paralogues in human: RN7SKP255 (77% identical), RN7SKP79 (77% identical), RN7SKP9 (77% identical), RN7SKP217 (77% identical), 7SK (76% identical), RN7SKP128 (76% identical), RN7SKP146 (76% identical), RN7SKP15 (76% identical), RN7SKP103 (75% identical), RN7SKP203 (75% identical), RN7SKP71 (75% identical), RN7SKP204 (75% identical), and 284 more.